FASN (fatty acid synthase)
Diseases named in the same sentence as FASN in open-access papers (continued):
Sharing a sentence is not in itself a finding about the gene and the disease.
Hepatic steatosis (continued). "The downregulation of FASN and SREBF1 is involved in hepatic steatosis." (PMID 38992651, 2024). "Therefore, an HF diet can induce higher expression of inflammatory cytokines and upregulate the protein expression levels of FASN, ACC1, CD36, ChREBP, and SREBP1c, thereby promoting the development of the fatty liver." (PMID 37095192, 2023). "Moreover, WBJ and BGE enhanced the activation of AMPK to reduce SREBPs, fatty acid synthase, and HMG-CoA reductase but increased the expression of CPT-I and PPARα to improve hepatic steatosis." (PMID 37630688, 2023). "The intracellular NAMPT inhibitor FK866 promoted liver steatosis in HFD-fed mice and hepatic lipid accumulation in vitro via the sirtuin 1 (SIRT1)/sterol regulatory element-binding protein 1 (SREBP1)/fatty acid synthase (FASN) pathway." (PMID 36009862, 2022). "Nuciferine treatment essentially reversed the HFD-induced increase in hepatic protein levels of SREBP-1c and fatty acid synthase (FASN), suggesting that nuciferine could attenuate the development of HFD-induced hepatic steatosis." (PMID 35873545, 2022). "FASN expression was correlated significantly with the degree of hepatic steatosis, but not with inflammation or ballooning of hepatocytes." (PMID 34419146, 2021). "In a rat model of hepatic steatosis induced by high fructose feeding, PBA intervention significantly lowered TAG content, suppressed lipogenic enzyme acetyl-CoA carboxylase (ACC), fatty acid synthase (FASN) and stearoyl-CoA desaturase (SCD) expression and improved ER stress." (PMID 32824248, 2020). "In conclusion, these results demonstrate that fatty acid synthase blockade constitutes a novel therapeutic strategy for altering hepatic steatosis at non-stressed states in obese livers." (PMID 24086674, 2013). "Several studies further suggest that fatty liver disease may facilitate CRC liver metastasis, potentially through the upregulation of fatty acid synthase (FASN) in the lipid-rich microenvironment, enhancing palmitate synthesis in CRC cells and thereby promoting hepatic metastatic potential." (PMID 40722777, 2025). "Since hepatic steatosis has been regarded as a driving force for insulin resistance and type 2 diabetes mellitus, the improved insulin sensitivity by TRIM21 could ameliorate hepatic glucose and lipid metabolic disorders by ubiquitination of FASN expression." (PMID 37249651, 2023). "An increase in SHP attenuated the triglyceride-dominated hepatic steatosis which was induced in vivo by a high-fat high-cholesterol (HFHC) diet and in vitro by free fatty acids depending on the inhibition of liver X receptor α (LXRα) and fatty acid synthase (FASN)." (PMID 36904254, 2023). "Upregulation of ACC and FASN expression may have contributed to the initial increase in hepatic adiposity in rats fed an ND, and activation of CD36 expression was responsible for the development of hepatic steatosis in rats fed an HFD." (PMID 32807074, 2020). "FK866 significantly promoted liver steatosis in the mice fed with HFD and hepatic lipid accumulation in vitro, accompanied by the increases of the expressions of lipogenic genes such as sterol regulatory element-binding protein 1 (SREBP1) and fatty acid synthase (FASN)." (PMID 28449683, 2017). "While ameliorating hepatic steatosis, cGAMP treatment significantly decreased the mRNA levels of liver acetyl-CoA carboxylase (ACC), an essential lipogenic enzyme, and an insignificant decrease in the mRNA levels of liver fatty acid synthase (FAS), also a lipogenic enzyme." (PMID 28743914, 2017). "Acetyl-CoA carboxylase 1 (ACC1), fatty acid synthase (FAS), 1-O-acylceramide synthase (ACS), 1-acyl-sn-glycerol-3-phosphate acyltransferase β (AGPAT2) and adipose triglyceride lipase (ATGL) have been reported to be crucial to TG metabolism in vitro and liver steatosis in vivo." (PMID 22675471, 2012).
Hepatic steatosis (continued). "However, the observation that neither the expression of FASn or the phosphorylation of ACC were increased in the liver tissue from the PC-fed mice indicated that the hepatic steatosis in this murine model was not occurring through the de novo lipogenesis pathway." (PMID 40806286, 2025). "In addition, MG741 regulated Acetyl-CoA carboxylase (ACC), fatty acid synthase (FAS), sterol regulatory element-binding protein 1 (SREBP-1), and carbohydrate-responsive element-binding protein (ChREBP) expression and lipid accumulation in the liver, thereby reducing the hepatic steatosis score." (PMID 35565930, 2022). "The TRIM56/FASN axis regulates hepatocyte lipid accumulation in Nonalcoholic liver disease and FASN inhibition protects mice against HFD-induced hepatic steatosis." (PMID 38206764, 2024). "The result showed that HSD can significantly activate the de novo synthesis of endogenous fatty acids [fatty acid synthase (FASN), ATP citrate lyase (ACLY), and acetyl-CoA carboxylase (ACC)] in the liver, although hepatic steatosis was not severe." (PMID 35928832, 2022). "Recent clinical data using FASN inhibitors, such as FT-4101 and TVB-2640, have inhibited DNL and robustly improved hepatic steatosis without elevating circulating TGs." (PMID 35052685, 2021). "The transcripts of ACACA, FASN, SCD, FADS2 and FABP1 in chickens with fatty liver were significantly increased compared with those in chickens without fatty liver." (PMID 29642504, 2018). "The lipoogenic genes including fatty acid synthase (FAS), acetyl-coenzyme A carboxylase 1 (ACC1), and diacylglycerol acyltransferase (DGAT) decreased in tunicamycin-treated HepG2 cells and mice even though the mice had hepatic steatosis (data not shown), which was consistent with previous reports." (PMID 26540043, 2015).
ovarian carcinoma (120 papers, 2010 to 2026). A malignant neoplasm originating from the surface ovarian epithelium. "YY1 also stimulates the FASN-HIF1α pathway, causing ferroptosis suppression and the growth of ovarian cancer by inducing USP43." (PMID 41009346, 2025). "It was also demonstrated that high expression of FASN in ovarian cancer caused defective antigen presentation function of DCs, and consequently lower stimulatory effect for T cell proliferation." (PMID 40709184, 2025). "FASN was highly expressed in ovarian cancer, was associated with poor survival rate, and is upregulated in OCa and supports membrane biosynthesis, oncogenic signaling, and redox balance." (PMID 40868085, 2025). "Our study provides inaugural evidence that USP43 orchestrates ferroptosis susceptibility in ovarian cancer, mechanistically delineating its governance of the FASN-HIF1α-SLC7A11 signaling axis." (PMID 40890129, 2025). "Cancer cell-intrinsic FASN prevents anti-tumor immunity by reducing the ability of dendritic cells to maintain T cells in ovarian cancer and has been associated with reduced immune infiltration in gastric cancer." (PMID 39349429, 2024). "FASN has been shown to be highly expressed in ovarian cancer tissue, with higher expression linked to decreased survival rates." (PMID 36230617, 2022). "FASN catalyzes the synthesis of FAs, and elevation in the expression of FASN is associated with cancer progression in breast and ovarian cancer." (PMID 36149760, 2022). "Several studies have demonstrated that inhibition of FASN prevents the growth of the immunosuppressive phenotype associated with a variety of cancers including ovarian cancer, further implicating its critical role in tumorigenesis." (PMID 35634242, 2022). "More recent work suggests that FASN expression is associated with worse outcomes in cancers, including ovarian cancer." (PMID 35634242, 2022). "FASN, which is upregulated in ovarian cancer tissues, is associated with poor prognosis and survival." (PMID 35216285, 2022). "The Kaplan-Meier plotter tool revealed that FASN was associated with poor RFS (P = 0.0093) outcome for ovarian cancer and poor OS (P = 1e-08), FP (P = 1.2e-06), and PPS (P = 0.019) prognosis for lung cancer." (PMID 34879004, 2021). "FASN is highly expressed in ovarian cancer tissues and is associated with poor prognosis and survival rate." (PMID 33194756, 2020). "High expression of FASN in ovarian cancer cells also caused defects in the ability of dendritic cells to present antigens and prime T cells in ascites." (PMID 33194756, 2020). "Depletion of FASN in ovarian cancer cells by shRNAi caused the reduced content of long chain fatty acids in both OCM and DMEM by twofolds when compared with the scrambled controls (SC)." (PMID 31372520, 2019). "The upregulation of FASN has been linked to the acquisition of resistance to chemotherapy in breast and ovarian cancers; however, there is limited information about an association between FASN and endocrine resistance." (PMID 30180878, 2018). "In this study, we have demonstrated that FASN was upregulated in human ovarian cancer and associated with the immunosuppressive microenvironment." (PMID 30619288, 2018). "For example, increased expression of FASN is associated with resistance to cisplatin in breast and ovarian cancers and the resistance can be reversed by blocking FASN with an inhibitor, C75." (PMID 29996946, 2018). "FASN also serves as a potential diagnostic and prognostic biomarker as it is secreted in the blood of patients with breast, prostate, colon and ovarian cancers compared with normal healthy subjects." (PMID 27270654, 2016). "In the present study, we establish an association between the prognosis of patients with ovarian cancer and FASN/HER2 expressions in ovarian tissue." (PMID 25433947, 2015).
ovarian carcinoma (continued). "The present results revealed that the intensity of FASN expression and survival rate of ovarian cancer patients were closely linked, although further study is necessitated to ascertain the critical role of FASN as a prognostic marker for ovarian cancer." (PMID 25433947, 2015). "Our results show that increased FASN is associated with the peritoneal metastasis of ovarian cancers." (PMID 24979135, 2014). "In this study, we provide new evidence that homodimerization of NAC1, a drug resistance-associated nuclear protein, is essential for maintaining FASN expression at both protein and mRNA levels in ovarian cancer cells." (PMID 20508725, 2010). "For example, FASN inhibition has been shown to selectively activate AMP-activated protein kinase (AMPK) in ovarian cancer cells causing cytotoxicity while sparing most normal human tissues from these pleiotropic effects of AMPK activation." (PMID 20508725, 2010). "As with other epithelial cancers of the breast, colon, and prostate, FASN overexpression in ovarian cancer, as this study shows, appears to be associated with the most malignant type, that is, high-grade serous carcinoma." (PMID 20508725, 2010). "FASN was highly expressed in ovarian cancer and was associated with poor survival rate." (PMID 37110218, 2023). "Indeed, in ovarian cancer FASN expression has been associated with an immunosuppressive immune microenvironment." (PMID 37180110, 2023). "Furthermore, clinical data from patients with ovarian cancer showed that immunosuppression is frequently associated with increased FASN expression." (PMID 36555243, 2022). "The FASN gene (lipid biosynthesis) of cluster 1 encodes a key metabolic enzyme in lipogenesis whose elevated expression has been associated with intratumoral T cell depletion in advanced-stage ovarian cancer." (PMID 32117236, 2020). "Moreover, increased expression of FASN was shown to induce transition of the epithelium, thereby, causing cancer growth, increased number of metastatic ovarian cancer cells in the peritoneal cavity, and less success of tumor surgery." (PMID 33112541, 2020). "However, the impact of aberrant expression of FASN on metastases remains in infancy and the detailed mechanism underlying the metastasis of ovarian cancer needs to be elucidated." (PMID 24979135, 2014). "FASN overexpression causes resistance to the anticancer drugs adriamycin and mitoxantrone in breast cancer cells, gemcitabine-resistant pancreatic cells, cisplatin-resistant ovarian cancer cells, and radiotherapy resistant head and neck squamous cell carcinomas." (PMID 30456204, 2018). "High expression of fatty acid synthase (FASN) correlates with unfavorable outcomes in ovarian cancer, and elevated circulating fatty acids are being investigated as diagnostic indicators." (PMID 41567203, 2025). "Existing studies have shown that FASN overexpression occurs in various human cancers, including prostate cancer, ovarian cancer, colon cancer, lung cancer, endometrial cancer, and gastric cancer, among others." (PMID 41421797, 2025). "Although FASN is high in ovarian cancer, its prognosis seems to differ amongst histological subtypes." (PMID 40868085, 2025). "The ectopic FASN stimulated growth in ovarian cancer cells, and the FASN levels and lipogenic activities were reported to affect cellular lipid composition." (PMID 40868085, 2025). "Studies have shown that combining radiotherapy with FASN inhibitors increases cancer cell death, particularly in tumours with elevated FASN expression, such as breast, prostate, and ovarian cancers." (PMID 39796683, 2024). "The likely mechanism is that the SREBP-1c/FASN signaling pathway regulates the energy metabolism of SK-OV-3 ovarian cancer cells, thus inhibiting their proliferation." (PMID 38633612, 2024). "Inhibiting FASN was partially restoring the immunostimulatory ability of the DC in a mouse model of ovary carcinoma." (PMID 37180110, 2023).
ovarian carcinoma (continued). "For example, the combined treatment of low toxic AMP-activated protein kinase (AMPK) activator and fatty acid synthase inhibitor synergistically impeded ovarian cancer peritoneal metastases." (PMID 36860853, 2023). "Accordingly, fatty acid synthase (FASN) overexpression increases the peritoneal metastasis of ovarian cancers in mice, and promotes cellular colony formation and metastatic ability in vitro." (PMID 36980201, 2023). "Ovarian cancer cells utilize lipid metabolism in the ascites or omental microenvironment during metastatic progression through AMPK/ACC/FASN-mediated lipogenesis and AMPK/TAK1/NF-κB signaling pathways." (PMID 35634242, 2022). "C93, a FASN inhibitor, inhibited the growth of carboplatin/paclitaxel-resistant ovarian cancer cells." (PMID 35216285, 2022). "This suggested that aberrant overexpression of FASN is correlated with immunosuppressive status in ovarian cancer." (PMID 35216285, 2022). "Within these pathways are factors HIF-1α, IGFBPs, GLUT1, FASN, and leptin, which have all been demonstrated to be potential therapeutic targets in ovarian cancer." (PMID 36230617, 2022). "The upregulated expression of FASN ovarian cancer cell lines and primary cultures increases de novo fatty acid synthesis, cell growth, and cell viability, and enhances chemoresistance to cisplatin." (PMID 35216285, 2022). "Consistently, in ovarian cancer, FASN suppressed immune activity via decreasing the ability of dendritic cells to sustain T lymphocytes." (PMID 36428733, 2022). "Inhibition of FASN-mediated lipogenesis has been shown to exert powerful anti-tumor effects in a variety of cancers, including breast and ovarian cancers." (PMID 36555243, 2022). "Previous studies have reported that the inhibition of FASN exerts growth-inhibitory effects on ovarian cancer." (PMID 35216285, 2022). "In ovarian cancer, for instance, a FASN-related pathway was reported to disrupt dendritic cells and induce an impaired antitumor immune response via lipid accumulation." (PMID 35392075, 2022). "Treatment with C75 and G28UCM, which are the synthetic inhibitors of FASN, decreased ovarian cancer cell growth, and induced apoptosis." (PMID 35216285, 2022). "It has been reported that orlistat-mediated FASN inhibition reversed the resistance to taxane and cisplatin in prostate and ovarian cancer, respectively." (PMID 35742944, 2022). "In ovarian cancer cells, constitutively activating FASN compromised the capacity of tumour-infiltrating DCs (TIDCs) to support antitumour T cells and inhibiting FASN restored this capacity." (PMID 35448537, 2022). "Intriguingly, TAK1−/− ovarian cancer cells exhibited a marked reduction in FASN and CPT1A expression after OCM maintenance." (PMID 34638280, 2021). "Meanwhile, knocking down FASN dampens ovarian cancer invasion and migration both in vivo and in vitro." (PMID 35070947, 2021). "The upregulated FASN leads to an increase of fatty acids synthesis in ovarian cancer cells, and the high concentration of fatty acids in TME results in fatty acids accumulation in DCs, thus affecting its function." (PMID 33732237, 2021). "Studies on ovarian cancer have suggested that crucial enzymes that mediate metabolic reprogramming, such as FASN and CPT1A, are overexpressed in tumor tissues, which is associated with poor prognosis and survival rates." (PMID 34638280, 2021). "For instance, FASN enhances EMT in ovarian cancer through transcriptional regulation of E-cadherin and N-cadherin." (PMID 35070947, 2021). "A recent proteomics study has revealed the potential of fatty acid synthase (FASN) blockade to not only induce ovarian cancer cell death, but also exert an antiangiogenic effect." (PMID 34063807, 2021). "Further, the key enzymes of fatty acid synthesis metabolism were significantly expressed between ovarian cancer tissues and normal control tissues, including FASN, ACC1, and SREBP1." (PMID 34557266, 2021).